MMP14 (matrix metallopeptidase 14)
Diseases named in the same sentence as MMP14 in open-access papers (continued):
Sharing a sentence is not in itself a finding about the gene and the disease.
tumor (continued). "The worst prognosis was associated with low E-cadherin coupled with high MT1-MMP (MMP14), itself associated with tumour invasiveness in CRC." (PMID 21339979, 2010). "Dz13 upregulated the matrix metalloproteinase (MMP)-2 and MMP-9, and decreased expression of MT1-MMP (MMP-14) in cultured tumour cells." (PMID 20334687, 2010). "MMP14 reveals to be a very intriguing molecule that seems to be important in tumour progression by promoting cell invasion and matrix degradation." (PMID 19753302, 2009). "The results demonstrate that the relative expression levels of MMP-2 and MMP-14 of tumor samples were significantly higher than those of adjacent non-tumor tissue (p = 0.0202 and p < 0.0001, respectively)." (PMID 19144199, 2009). "RECK encodes a membrane-associated MMP regulator protein that is able to suppress tumor invasion and metastasis by negatively regulating MMPs involved in carcinogenesis, namely: MMP-2, MMP-9 and MMP-14 (MT1-MMP)." (PMID 19144199, 2009). "Staining of MMP-14 was clearly restricted to the cytoplasm of tumor cells and only very weak in stromal cells." (PMID 19531263, 2009). "This focal expression of Mmp13 in the tumor core was very different from the expression of Mmp2 and Mmp14, which were found throughout the tumor stroma, including at the tumor periphery, and in areas with hyperplasia, grade I and grade II MIN (not shown)." (PMID 18698413, 2008). "Notable exceptions were genes such as SPP1, HOXA10 and MMP14, for which the greatest differential increase in expression was at the comparative interface between thin and I.M. thickness tumor samples." (PMID 18442402, 2008). "We have previously reported that mRNAs for several MMPs, including Mmp2, Mmp3, Mmp11 and Mmp14 are expressed in the MMTV-PyMT tumor stroma." (PMID 18698413, 2008). "By multivariate analysis, using the Cox model adjusting for tumor size and number of involved lymph nodes, high MMP-14 expression was clearly a significant factor of poor survival." (PMID 16776850, 2006). "Of the three molecules, an adjusted Cox model revealed that high MMP-14 mRNA (≥ 10% cells) alone predicted a significantly shorter overall survival (p = 0.031) when adjusted for clinical factors (tumor size and number of involved lymph nodes)." (PMID 16776850, 2006). "In situ hybridization was carried out for the ets variant ETV4 (PEA3) (23 cases) as well as MMP-9 (19 cases) and MMP-14 (13 cases), demonstrating high mRNA expression in the tumor cells." (PMID 16042759, 2005). "Equally important will be understanding the relative contributions of centrosomal versus nuclear MMP-14 dysfunction to tumor cell lethality, which will inform whether inhibitors should target specific subcellular pools or global MMP-14 activity." (PMID 41542511, 2026). "Furthermore, We found that MMP14 expression increased with tumor stage (p=0.02), in contrast to most other cancers, prompting further investigation into its functional role in ACC." (PMID 41542511, 2026). "Thus, research has increasingly focused on designing selective inhibitors that target specific MMPs associated with tumor progression, notably MMP-2, MMP-9, and MMP-14." (PMID 40265458, 2025). "This was further supported by MMP-14 western blot analysis on ECM extracts from both tumor models." (PMID 40166338, 2025). "Additionally, tumor progression was monitored weekly using bioluminescent imaging, revealing that the tumor burden in the MMP14 knockdown group was lower than that in the control group." (PMID 40121502, 2025). "We designed wild‐type GSDMD (wt), GSDMD cleavage site mutant (mut), GSDMD‐C‐terminal (C), N‐terminal with membrane‐binding domain mutant (MCD), and N‐terminal cytotoxic domain (CD) plasmids to determine which domain of GSDMD regulates MMP14 expression and tumor metastasis in OSCC." (PMID 40178046, 2025). "As a transmembrane protein, MMP14 activates pro-MMP2 to induce tumor cell invasion." (PMID 40121502, 2025).
tumor (continued). "Its overexpression facilitates tumor invasion, angiogenesis, and metastasis, indicating that elevated MMP-14 levels may serve as an early indicator of malignant transformation." (PMID 40572725, 2025). "Additionally, MMP-14 probes have been used for the early detection of dysplasia in IBD, as MMP-14 plays a key role in tissue remodeling and tumor progression." (PMID 40429975, 2025). "Our study provides valuable insights into the differential expression of Maspin, β-catenin, and MMP-14 in oral lesions with malignant transformation potential, highlighting their distinct roles in tumor suppression, cellular adhesion, and extracellular matrix remodeling." (PMID 40572725, 2025). "Elevated levels of MMP-14 may correlate with tumor aggressiveness and serve as an important marker for identifying lesions with a high invasive potential." (PMID 40572725, 2025). "MMP14 protein levels are also stable in tumor versus non‐tumor tissues." (PMID 40985572, 2025). "A more defined role of antibody producing cells in HGSOC has been described, including production of autoantibodies directed to MMP14 overexpressed on tumor cells, and the role of antigen-specific and antigen-independent polyclonal IgA in directing the intratumoral immune response." (PMID 39910037, 2025). "Additionally, the expression of NOX5 and MMP-14 is upregulated in areas of the tumour that are in the proximity of the PPAT." (PMID 39941741, 2025). "MMP14 inhibition curbs tumor development in a CRC PDX model." (PMID 38329810, 2024). "Versican induces MMP14 expression through microglia, which favors tumor invasiveness." (PMID 38473812, 2024). "Targeting TANs by antibody-mediated depletion, pharmacological inhibition of trafficking, or specific suppression of MMP14 by an allosteric inhibitor potently disrupted tumor vascularization by suppressing new vessel outgrowth, branch architecture, and depth penetration." (PMID 38329810, 2024). "Additionally, AP-2α mediates the anti-tumor effects of small ubiquitin-like modifier (SUMO) inhibitors by downregulating CD44 and MMP14, restraining tumor stemness." (PMID 39273087, 2024). "Concomitantly, GBM cells upregulate MMP2 and MMP14 which facilitate tumor invasion." (PMID 38473812, 2024). "The G2 and G3 tumor samples contained substantially lower amounts of MMP-14." (PMID 39125675, 2024). "Mechanistically, UCA1 could increase the expression of MMP14 through sponging miR-485-5p, thereby promoting tumor metastasis." (PMID 38725621, 2024). "Inhibits angiogenesis and tumour progression by downregulating MMP14 expression." (PMID 39450176, 2024). "Moreover, MMP-14 expression varies with the tumor type and is high in melanomas, mesenchymal tumors and brain tumors, as well as in liver tumors and breast cancer." (PMID 39125675, 2024). "Furthermore, we show that uLMS tumours highly express various collagen‐remodelling genes, including collagen‐crosslinking and matrix metalloproteinase genes, particularly MMP14." (PMID 37078535, 2024). "Combining ex vivo cultures or decellularized tumours, representing the real TME in uLMS, may shed light on the function of MMP14 in tumours." (PMID 37078535, 2024). "Our data further demonstrate that targeting the pro-angiogenic TAN activity and specific MMP14 inhibition may provide promising therapeutic option to suppress tumor growth." (PMID 38329810, 2024). "In addition, a significantly higher specific activity of MMP-14 in tumor tissue was determined, compared to MMP-15." (PMID 39125675, 2024). "Thus, the progress in tumor invasiveness from tumor grade G2 to G3 involved a rather small decrease in the MMP-14." (PMID 39125675, 2024). "Moreover, MMP-14 not only promotes growth but also stimulates tumor angiogenesis by increasing the production of VEGF." (PMID 39582871, 2024).
tumor (continued). "Also, blocking CXCL10/TLR4/MMP14 signaling to inhibit MDSCs mobilization and tumor cells invasion and metastasis will present a great potential for developing novel treatment strategies against HCC malignant progression and recurrence." (PMID 37007125, 2023). "Another marker of aggressive tumor cells is the expression of matrix metalloproteinase 14 (MMP14)." (PMID 38046670, 2023). "Interestingly, several extracellular matrix protein genes predominantly expressed in CAFs, such as PLAU, MMP14, were also highly expressed in the mesenchymal-like tumor population (Tumor cells 3)." (PMID 37007745, 2023). "Moreover, M-MDSCs can suppress tumor immunity via the CXCL10/TLR4/MMP14 signaling, thereby increasing tumor recurrence after liver transplantation." (PMID 36773210, 2023). "Altogether, these results suggest that the protease MMP14 can boost the migration of γδ T cells in the ECM-enriched tumor environment, and might thereby help to overcome limitations that hamper γδ T-cell migration in vivo and, ultimately, therapy outcome." (PMID 37139603, 2023). "The bioactive nanoMelittin could be released specifically in an MMP14-responsive manner at tumor sites and then form pores in membranes and disturb phospholipid bilayers of tumor cell membranes." (PMID 38017537, 2023). "Notably, mCAFs highly expressed tumor invasion-associated genes (FAP, MMP1, MMP14, and POSTN), commonly associated with ECM remodeling and cell migration during tumor metastasis, thus reflecting the importance of mCAFs in the metastatic TME." (PMID 37853464, 2023). "Strikingly, there was a strong correlation between the levels of MMP14 and tumour growth." (PMID 36892272, 2023). "MMP14 is also named as membrane type 1 matrix metalloproteinase, which participates in the degradation of basement membrane and extracellular matrix and thus promotes tumor invasion and metastasis." (PMID 37488455, 2023). "In addition to Hif1a and Vegfa upregulation, MDM-B showed differential expression of Mmp12, Mmp14, and Igf1, which were also part of the tumor microenvironment pathway." (PMID 37858232, 2023). "Furthermore, MMP14 has been intensively studied in the process of tumor-cell migration where it was shown to possess promigratory functions." (PMID 37139603, 2023). "Bivariate analysis revealed a significant association between ENE + and c/pDOI > 10 mm and between ENE + and MMP14 expression in the tumour nest (high) and CAFs (positive); the analysis was based on the co-scoring system (high risk) in biopsies and resected specimens (all p < 0.05)." (PMID 36765296, 2023). "Finally, adipocytes areincluded in tumor stroma and have major roles in tumor progression via releasing MMP-14,7,10, 1, and 11 that alter the ECM." (PMID 36833401, 2023). "MMP14 over-expressing tumours grew and metastasised aggressively." (PMID 36892272, 2023). "MMP-14 contributes to collagen digestion around tumor cells and favors cell invasion and migration." (PMID 38201509, 2023). "Furthermore, direct immunoblot analysis of protein expression in lung tissue homogenates from wt mice demonstrates enhanced expression of RECK and decreased expression of MMP14 in rTIMP2-treated and tumor-free compared with vehicle control treated (HBSS) mice." (PMID 38234759, 2023). "Likewise, increased presence of MMP14 stimulates infiltration of surrounding tissues for tumor progression." (PMID 38046670, 2023). "In addition, their analysis showed that the upregulation of MMP11, MMP14, MMP17, and MMP19 is significantly associated with a more advanced tumor stage and a worse long-term prognosis." (PMID 37511338, 2023). "In addition, a higher percentage of cells per time-lapse experiment was in direct tumor contact when the cells expressed MMP14 and a bigger fraction of γδ T cells resided in the tumor for more than 50% of their monitored time when expressing MMP14 (right)." (PMID 37139603, 2023).
tumor (continued). "Due to the MMP14 responsive linker between hGC33 scFv and melittin, melittin could be released specifically at MMP14‐expressing tumor sites." (PMID 38023709, 2023). "The bioactive and targetable nanomelittin conjugated by hGC33 scFv could be released in an MMP14‐responsive manner at tumor sites, which reduced off‐target toxicity, especially the hemolytic activity of melittin." (PMID 38023709, 2023). "In addition to soluble MMPs, CD44 can form a protein complex with the membrane bound MMP14 (aka MT1-MMP) at the cell surface, thereby directing it to the leading edge of migrating cells and promoting tumor cell invasion." (PMID 36876041, 2023). "Furthermore, the miR-150/ MMP14 regulation pathway can be modulated by lncRNAs during tumor cell migration." (PMID 37924077, 2023). "Therefore, a co-scoring system based on MMP14 expression in the tumour and CAFs at the TSI comprehensively demonstrates the response of the TME activity." (PMID 36765296, 2023). "In addition, MMP14 expression in the tumour nest of biopsy specimens showed a high predictive value for predicting ENE+ (sensitivity, 80%; specificity, 72%; PPV, 42%; NPV, 93%; accuracy, 72%; AUC = 0.811; 95% CI, 0.688–0.934)." (PMID 36765296, 2023). "This mIHC-based spatial profiling also suggested that the tumor aggressiveness conferred by MMP14+ CAFs might by explained, at least in part, by promotion of the infiltration of M2-TAMs into the TN by these cells." (PMID 36052235, 2022). "Notably, the relation between MMP14 expression and tumor-infiltrating lymphocytes (TILs) was investigated in several cancers." (PMID 35572966, 2022). "MMP14 is up-regulated in PCa cells, and may be involved in mediating the mutual crosstalk between PCa cells and periprostatic adipose tissue, promoting tumor invasion." (PMID 35280985, 2022). "Although we did not examine matrix components such as collagen and laminin, changes in the peritumoral matrix composition may have contributed to the modulation of tumor progression by MMP14." (PMID 36052235, 2022). "CLIC2 inhibits tumor cell invasion and metastasis by suppressing MMP14 activity." (PMID 36230813, 2022). "MMP2 and MMP14, affecting the top enriched biological functions, were mainly expressed in iCAFs and can promote extracellular matrix degradation and tumour cell invasion." (PMID 35184420, 2022). "In contrast, Musashi 1 and MMP14 staining revealed only a few positive cells, mainly in the tumor border, which could possibly reflect an invasion zone." (PMID 36230481, 2022). "In addition, subcutaneous xenograft nude mouse models confirmed that the growth of tumours was weakened by knock‐down MMP14 and INHBA." (PMID 35150061, 2022). "The effect of MMP-14 on tumor initiation has also been reported." (PMID 36741729, 2022). "MMP14 staining revealed only a few positive cells, mainly in the tumor border, which could reflect the invasive front in both models." (PMID 36230481, 2022). "In addition, a preclinical study showed that inhibition of MMP14 activity resulted in suppression of M2-TAMs and tumor regression." (PMID 36052235, 2022). "Death receptor 6 (TNFRSF21) has been reported to have inhibitory effects on monocyte differentiation when cleaved from the surface of tumor cells by matrix metalloproteinase 14 (MMP14), the latter being expressed about 10-fold higher in ncM and intM (data not shown)." (PMID 35967310, 2022). "Thus, MMP-14 expression promotes migration, invasion and metastasis of tumor cells in vitro and in vivo." (PMID 35201460, 2021). "Several intracellular and intranuclear substrates and interaction partners have been reported for MMP-14, such as pericentrin, a component of chromosomal centrosomes, centrosomal BRCA2, a DNA repair-associated tumor suppressor, the cytoskeletal proteins ezrin and moesin, and glycolytic enzymes." (PMID 35008569, 2021).
tumor (continued). "Our studies further certified that deficiency of CXCL10/TLR4 or TLR4 inhibitors could effectively reduce the monocytic MDSC recruitment with decreased MMP14, leading to the smaller tumor occupation." (PMID 33990548, 2021). "This study aims to explore the correlation between MMP14 and pan-cancer prognosis, immune infiltration, and the effects of pan-cancer gene mismatch repair (MMR), microsatellite instability (MSI), tumor mutational burden (TMB), DNA methylation, and immune checkpoint genes." (PMID 34604053, 2021). "MMP14 is used in the tumor microenvironment and promotes tumor invasion and metastasis." (PMID 34007838, 2021). "Currently, there are still limited studies investigating whether MMP14 is related to tumor prognosis or can be a biomarker for biological prognosis." (PMID 34604053, 2021). "As a matter of fact, MMP14 is being considered in areas such as tumor invasion of several organs." (PMID 34361079, 2021). "Besides its role in maintaining tissue homeostasis, MMP14 is up-regulated in many tumors and promotes their progression by regulating cellular processes such as proliferation, migration, and tumor cell invasion." (PMID 34830157, 2021). "All of these results fully indicate that MMP14 may be a biomarker for the prognosis, diagnosis, and treatment of many tumors and provide a new idea and direction for subsequent tumor immune research and treatment strategies." (PMID 34604053, 2021). "The fibril-forming collagen types I, II, and III, in particular, and other ECM proteins such as fibronectin, vitronectin, fibrinogen and fibrin, nidogen, BM laminins, and laminin-332, which is ectopically expressed in the tumor stroma, are substrates of MMP-14." (PMID 35008569, 2021). "We investigated the relationship between the expression of MMP14 in tumors and tumor prognosis, the relationship between MMP14 expression and tumor cell immune infiltration, and the relationship between MMR gene MMR, MSI, TMB, DNA methylation, and immune checkpoint genes." (PMID 34604053, 2021). "The results of this study suggest that MMP14 plays a critical role in tumor immunity and may serve as an important biomarker." (PMID 34604053, 2021). "Furthermore, ADAM12 reduces tumor cell apoptosis and promotes tumor growth by redistributing and activating MMP14, resulting in gelatin degradation." (PMID 34604068, 2021). "Also, in the clinicopathological and prognosis analyses, upregulated MMP11, MMP14, MMP17, and MMP19 were significantly associated with a higher tumor stage and a worse prognosis." (PMID 34804973, 2021). "Thus, the overexpression of MMP14 not only facilitated tumor cell invasion but also mobilized MDSCs to the liver graft promoting HCC recurrence after transplantation." (PMID 33990548, 2021). "It has also been suggested that MMP14 can be used as a biological indicator of tumor prognosis." (PMID 34604053, 2021). "Additionally, untreated control neoplasms revealed a smaller MMP-14 immunopositive area at 44 dpt compared to DH82-UV-CDVai tumors (p < 0.0001)." (PMID 33808256, 2021). "MMP-14 also shows the anti-apoptotic function and thereby promotes tumor growth." (PMID 34912809, 2021). "In our study on lymphogenic and hepatogenic metastasis, all tumours were MMP-14 positive." (PMID 34344453, 2021). "All of these results fully indicate that MMP14 may be a biomarker for the prognosis, diagnosis, and treatment of many tumors and provide new ideas and direction for subsequent tumor immune research and treatment strategies." (PMID 34604053, 2021). "Lumican, a small, leucine-rich proteoglycan, can directly bind to and inhibit MMP-14 and, hence, may limit tumor progression by preventing collagen degradation and invasion." (PMID 35008569, 2021). "MMP-14 is essential for pericellular collagenolysis and remodeling of tumor stroma." (PMID 35008569, 2021).